ISG15 (ISG15 ubiquitin like modifier)
Diseases named in the same sentence as ISG15 in open-access papers (continued):
Sharing a sentence is not in itself a finding about the gene and the disease.
tumor (continued). "Increased ISG15 expression was correlated with tumor recurrence and poor prognosis, which could be due to its capacity to promote CSC phenotype and radioresistance and chemoresistance in NPC." (PMID 26919245, 2016). "Given the high incidence, suboptimal therapeutic response, and poor prognosis of patients with cancers of the digestive system, elucidating the effects of secreted ISG15 on local tumor immunity should also be considered an important objective for future research." (PMID 27626310, 2016). "Because ISG15 induced stem-like properties and correlated with tumor recurrence and shorter survival, we further validated whether ISG15 may confer resistance to radiation and chemotherapy." (PMID 26919245, 2016). "The findings of these studies collectively suggest that the contribution of ISG15 to tumor chemosensitivity may be indirect and tissue specific." (PMID 27626310, 2016). "However, our results that ISG15 induces NK cell infiltration and tumor regression, and literature reports that NK cells have the ability to kill tumor cells and free ISG15 activates NK cells in culture, suggest such a possibility." (PMID 25749047, 2015). "Together, our results suggest that extracellular free ISG15 stimulates infiltration of NK cells, which in turn, may lead to suppression of tumor growth in nude mice." (PMID 25749047, 2015). "We therefore tested whether addition of purified recombinant free ISG15 extracellularly was capable of stimulating chemotaxis and migration of NK cells into tumors to inhibit tumor growth in nude mice as a means of simulating secretion of the polypeptide." (PMID 25749047, 2015). "Because recombinant ISG15 is known to stimulate the proliferation and activation of NK cells in culture, we examined the possibility of ISG15 secretion from the tumor cells and activation of NK cells as a plausible reason for the regression of ISG15 overexpressing tumors in nude mice." (PMID 25749047, 2015). "Indeed, expression of free ISG15 and ISG15 conjugates is heterogeneous in human solid tumors and tumor cell lineages." (PMID 25749047, 2015). "Interestingly, we observed almost complete suppression of the MDA/LV-control xenograft tumor growth in nude mice injected with free ISG15 (closed triangles)." (PMID 25749047, 2015). "Moreover, the expression of ISG15 is with a high degree of heterogeneity in both tumor cell lines and tumor tissues." (PMID 25238261, 2014). "We generated a siRNA against ISG15 and performed intratumor injection in tumor-bearing mice." (PMID 25238261, 2014). "Interestingly, ISG15 silencing affected tumor microenvironment including MVD and cytokines such as VEGF and IL-6." (PMID 25238261, 2014). "Next, we determined whether ISG15 overexpressed in HCC specimens compared to non-tumor counterparts." (PMID 25238261, 2014). "To further investigate whether ISG15 affects the tumor microenvironment, we detected microvessel density (MVD) and cytokines such as vascular endothelial growth factor (VEGF) and Interleukin-6 (IL-6) in mouse models of HCC." (PMID 25238261, 2014). "We have also asked the question whether the elevated ISG15 expression in tumor cells could be due to oncogene activation." (PMID 21897875, 2011). "The demonstration of ISG15 as a tumor marker immediately suggests that the type I IFN signaling pathway may be up-regulated in tumors." (PMID 21897875, 2011). "ISG15 is astress-response gene that may function as a tumor suppressor and contributor toinflammatory responses." (PMID 20157543, 2009). "ISG15 regulation may be one mechanism bywhich telomere shortening suppresses tumor formation prior to the telomeresbecoming sufficiently short to cause problems of genomic instability." (PMID 20157543, 2009).
tumor (continued). "However, alterations in the ISG15 signalling pathway have also been found in several human tumour entities." (PMID 18627608, 2008). "In comparison, we found the ISG15 protein upregulated in nearly all of the tumours analysed in the study; it was overexpressed in 93% (26 out of 28) of Ta tumours, 100% (20 out of 20) of T1 tumours, and 98% (44 out of 45) of T2–T4 compared to the normal tissue samples." (PMID 16641915, 2006). "These cells may arise from the many blood vessels present in the tumour tissue; in support of this prediction, ISG15-positive cells were observed within tumour-infiltrating blood vessels." (PMID 16641915, 2006). "Moreover, measuring ISG15 mRNA transcript level in peripheral blood (commonly referred to as liquid biopsy) has the advantage of being more practical than measuring ISG15 expression in tumor-tissue." (PMID 40936712, 2025). "Additionally, ISG15 is associated with tumor angiogenesis, as its inhibition in certain cancers reduces the secretion of angiogenesis-related factors such as VEGF and IL-6, leading to suppressed tumor growth and invasiveness." (PMID 40208307, 2025). "ISG15 and protein ISGylation conjugates affect the physiological states of tumors in a manner dependent on internal and external stimuli and orchestrate tumor–tumor microenvironment communication during cancer development, resulting in tumor progression or tumor suppression." (PMID 38443596, 2024). "However, it is not clear how ISG15 promotes tumor-associated phenotypes in our study, nor is it in previous reports." (PMID 38385083, 2024). "Also, the substrate‐conjugating enzymes (E3 ligases) may be involved in the conjugation of critical oncogenic substrates with ISG15 preventing their lysosomal clearance and therefore promoting stability to drive tumour progression and metastases in HGSOC." (PMID 38939897, 2024). "However, it remains uncertain whether ISG15 and ISGylation play a pro-tumor or anti-tumor role in cancer." (PMID 37217923, 2023). "Therefore, the deregulation of ISG15 expression may display pro- and anti-tumor activities depending on the cancer type." (PMID 37711589, 2023). "Intriguingly, while ISG15-mediated restoration of fork protection has been consistently observed in all cellular systems we have tested, the acquisition of drug resistance appears to be rather tumor and cell type-specific, probably depending on the complexity of the genetic background." (PMID 37783689, 2023). "This regulation of ISG15 expression may therefore promote tumor suppression before additional mechanisms of DNA repair are triggered, and impaired ISG15 upregulation due to telomere ablation could contribute to the initiation and progression of age-associated diseases." (PMID 37025175, 2023). "Therefore, the anti-tumor role of ISG15+ macrophages require further studies." (PMID 37492578, 2023). "ISG15 secretion from tumor cells, M2 macrophages, or alternatively activated macrophages suppresses adaptive immunity and promotes tumorigenesis, indicating that ISG15 acts as a tumor microenvironment factor in tumor progression and cytotoxic immune suppression." (PMID 36319753, 2022). "Moreover, IFN-mediated ISG15 expression is governed by several tumor suppressors and oncogenes." (PMID 35159348, 2022). "However, ISG15 was reported as an endogenous tumor suppressor but, when dysregulated in cancer cells, may be subverted to promote tumorigenesis." (PMID 36500393, 2022). "Furthermore, ISG15 protein might be expressed in other cells; however, this is beyond the scope of this study which focuses mainly on the expression in tumour epithelial cells." (PMID 33073304, 2021). "Moreover, when we distributed the protein expression of ISG15 according to BC tumour IHC subtypes, high protein expression of ISG15 showed a significant association with ductal no special type (NST) BC tumour compared to lobular BC type (p = 0.003)." (PMID 33073304, 2021).
tumor (continued). "Moreover, ectopic ISG15 expression suppressed tumour formation in nude mice." (PMID 33797839, 2021). "Therefore, targeting ISG15 pathway may potentially help to find new avenues that can be useful to precisely inhibit the tumour progression using personalised medicines." (PMID 33073304, 2021). "In the current study, there is a high immune response illustrated by high expression of CD8, FOXP3 and CD68, which play an important role in tumour microenvironment and immune response, to ISG15 protein expression which may also support the role of ISG15 in controlling tumour microenvironment in BC." (PMID 33073304, 2021). "ISG15 has been postulated that it may directly or indirectly be involved in tumor development." (PMID 31309113, 2019). "Nairoviruses and arteriviruses have shown to encode ovarian tumor domain (OTU)-containing proteases that hydrolyze ISG15 from target proteins and severe acute respiratory syndrome (SARS) coronavirus encoded the papain-like protease that cleaves both ubiquitin and ISG15." (PMID 27564865, 2016). "Whether ISG15-dependent NK cell infiltration observed in the current study is causally responsible for tumor regression in nude mice is not known." (PMID 25749047, 2015). "However, detailed effects of ISG15 and its enzymes in tumor suppression are yet to be explained." (PMID 23109884, 2012). "Dual suppression of ISG15 and HMGCR triggered synthetic lethality, effectively eradicating CSCs and impairing tumor progression." (PMID 41366470, 2025). "For instance, IFIT1, IFIT3, IFI-16, ISG15, MX1, and OAS1 have been shown to have tumor-suppressive function." (PMID 40563638, 2025). "Clinically, tissue microarray analyses of human and murine PC specimens confirmed that elevated ISG15 and HMGCR protein levels correlate with advanced tumor grades, despite unchanged mRNA expression post-ISG15 knockdown." (PMID 41366470, 2025). "Then the ISG15-RAGE axis was blocked by either knockdown of necroptotic-ISG15 release and RAGE inhibitor FPS-ZM1, and the impact on tumor progression were tested." (PMID 38926796, 2024). "The expression of both ISG15 and USP18 were significantly increased in the primary and metastatic tumour when compared with control mice ovarian tissue as analysed by ELISA." (PMID 38939897, 2024). "The results revealed that Mn‐N/C plus H2O2 treatment notably stimulated high expression levels of IFNα, IFNβ, and ISGs including Irf7, Isg15, and Cxcl10 in MC38 tumor cells." (PMID 38308189, 2024). "Western blot analysis of tumor tissue lysates showed elevated OPN, PD-L1, p21Cip1, c-Myc, survivin, CD44, and ISG15 upon irinotecan treatment." (PMID 39456585, 2024). "Treatment with recombinant human ISG15 induced NF-κB and STAT3 activation, tumor-cell EMT, and promoted tumor-cell migration and invasion in vitro." (PMID 38926796, 2024). "Young Joo Jeon at Chungnam National University College of Medicine, Daejon, South Korea, and co-workers found that ISG15 can conjugate to another protein, SIRT1, which also affects tumor growth and response to treatment." (PMID 38443596, 2024). "Six tumor-infiltrating CD4+ T-cell clusters (CD4+_FOXP3, CD4+_CCR7, CD4+_LMNA, CD4+_ISG15, CD4+_CXCL13 and CD4+_MKI67) were identified after data filtering, integration, unsupervised clustering and annotation." (PMID 38383773, 2024). "The results indicated that CXCL10 and ISG15 were up-regulated in LUAD, LIHC, and COAD compared to the non-tumor group." (PMID 38953994, 2024). "Accordingly, the mRNA expression of IFNβ, CXCL10, ISG15, and IFIT1 in the tumor tissues was analyzed." (PMID 39170700, 2024). "One week after tumor cells injection, Gemcitabine or control (PBS solution) was provided to investigate the impact of ISG15 on chemotherapeutic sensitivity." (PMID 38385083, 2024). "In contrast, compared to normal tissues, tumor tissues showed noticeably elevated expression levels of SAA1, MDK, and ISG15." (PMID 39440053, 2024).
tumor (continued). "Notably, re-emerged clonotypes in ISG-15+CD8+ T cells after treatment among EBV (+) patients were detected and associated with effector T population expressing CXCL13 in responsive EBV (+) tumor, indicating their significant importance in tumor immunochemotherapy response." (PMID 39334490, 2024). "Consistently, in our study, P. intermedia-induced ISG15 upregulation in xenografts of OSCC was demonstrated by transcriptome sequencing and IHC analysis of tumor tissue." (PMID 38644421, 2024). "Further, we also evaluated the anti-tumor effect of Lm-LLO-ISG15, a Lm-based vaccine targeting ISG15." (PMID 36831577, 2023). "We selected four ISGs, OAS1, ISG15, MX1 and IFI6, for further validation by Taqman Q-RT-PCR in the HCC tumor tissues." (PMID 37686559, 2023). "Our data from tumor cell and CD4+ T lymphocytes co-culture experiments showed that ISG15 can stimulate the differentiation of Th1 subtype CD4+ T cells and a elevated secretion of IFN-γ." (PMID 37217923, 2023). "Focusing on ICI-responsive GCs, we found a substantial proportion of pre-treatment ISG-15+CD8+ T clonotypes in effector T-cell populations (CXCL13+CD8+ T, ZNF683+ Tem and GZMK+ Tem) of post-treatment EBV (+) tumours." (PMID 37735150, 2023). "On the contrary, the tumor of Lv-ISG15 groups, Ki67 and CD31 staining were weak, and numbers of CD3+, CD4+ and CD8+ tumor-infiltrating lymphocytes were significantly reduced." (PMID 37217923, 2023). "We generated myeloid-specific Usp18-KO mice that have an additional deletion of Isg15 (Usp18Δ/ΔIsg15−/−) and repeated tumor growth studies using B16F10 and EL4 tumor cells." (PMID 38100351, 2023). "Another example is ISG15 upregulation in endometrial carcinoma to promote MYC proto-oncogene (MYC) signaling and changes in the DNA methylation profile, leading to pro-tumor actions and a poor prognosis." (PMID 37711589, 2023). "We first analyzed the TCGA dataset and found statistically significant differences in the expression of activated CD4+ memory T cells, CD8a+ in tumor cell infiltration and CD8+T lymphocyte cytotoxic factors in tumor tissues with high/low ISG15 expression." (PMID 37217923, 2023). "Particularly, two interferon-stimulated factors (ISG15 and ISG20) are also found contributing to tumor growth and metastasis." (PMID 37483625, 2023). "And we also confirmed that over-expression of ISG15 can increased the number of CD4+ and CD8+ T cells in spleen and the cytotoxicity of tumor-infiltrating lymphocytes in Lewis’s xenograft models." (PMID 37217923, 2023). "On the other hand, those spots within the tumor parenchyma expressed more tumor cell genes (e.g., PMEL) and IFN-stimulated genes (e.g., ISG15, IFITM3, IFI6), confirming their closeness to tumor cells and IFN activation." (PMID 37655659, 2023). "We observed a small cluster of tumor cells (c9) that exhibited a gene expression pattern (OAS1, ISG15, OAS2) consistent with an interferon (IFN) response gene signature." (PMID 37609233, 2023). "ISG15 (IFN-stimulated gene), a ubiquitin-like protein, has been shown to be a tumor-related gene involved in tumors pathogenesis." (PMID 37601683, 2023). "ANKRD13B, ISG15, KBTBD12, KLHL35, and UHRF1 were upregulated in tumor samples; DCUN1D5, HCK, and SOCS3 were downregulated in tumor than in normal samples." (PMID 35884544, 2022). "Macrophage clusters from different tumor types were diverse; additionally, SPP1+, C1QC+, ISG15+, and FN1+ TAMs were primarily enriched at the tumor site." (PMID 35504878, 2022). "Therefore, the effects of ISG15 on CSCs may be tumor context-dependent." (PMID 35455671, 2022).
tumor (continued). "According to the Pearson correlation analysis, the two DEGs, including ISG15 and ZFP36, were closely correlated with tumor-infiltrating immune cell subsets, suggesting the involvement of prognostic genes in the immune response in PCa progression." (PMID 35538543, 2022). "The IFIT1, ISG15, IFITM1 and IFI27 genes are related to activation of the interferon gamma (IFNγ) response, suggesting possible inflammatory responses in NR tumour samples." (PMID 35053540, 2022). "The inverse correlation of both ISG15 and UBC8 expression with disease-free survival suggested that conjugated ISG15 enhances metastasis and tumour progression." (PMID 34556814, 2021). "Meanwhile, Abx treatment inhibited the expression of type I interferon (IFNβ), and ISGs (MX1, ISG15, and IFIT1) in small intestine and tumor tissues, validating its regulation on IRF3 activation." (PMID 33188184, 2020). "Clinically, ISG15+ CD163+ TAMs related to impaired survival of patients and advanced tumor stage of NPC." (PMID 33424843, 2020). "ISG15, an interferon (IFN)-inducible, ubiquitin-like protein, was overexpressed in TNBC tumours that developed CNS metastases." (PMID 30792808, 2019). "In turn, CSCs were found to secrete IFN-β, inducing further expression of ISG15 by TAMs, as well as TGF-β1, Nodal and Activin that polarize macrophages towards a pro-tumor M2-like phenotype." (PMID 29373514, 2018). "Future studies to evaluate the effects of ISG15 on tumor growth and immune response by manipulating the presences of different immune cell types, including NK cells, in animal models could provide valuable insight into the roles of ISG15 in the immune tumor microenvironment." (PMID 30469497, 2018). "Among the eight down-regulated genes, one is an oncogene (NEAT1), six are tumor-suppressor genes (ASS1, PTPRD, ISG15, TGFBI, SELENBP1, MEG3) and one gene serves as both an oncogene and tumor-suppressor gene (CDH17)." (PMID 30563222, 2018). "Xenograft studies further demonstrated that similar to DTX3L knockdown, knockdown of either LIPG or ISG15 completely abolished the DTX3L overexpression-enhanced growth of MDA-MB-468 xenograft tumors and also significantly inhibited tumor development." (PMID 29350614, 2018). "Consistently, CD44, OAS3, ISG15, STAT1, and WNT5A were significantly upregulated whereas KIT was significantly downregulated in tumor compared to normal in GSE13861." (PMID 30134903, 2018). "We also analyzed expression of ISG15 mRNA in HCC tissue specimens and in adjacent non-tumor liver tissues retrieved from 36 primary HCC patients." (PMID 27626177, 2016). "Knocking down ISG15 inhibits HCC cell proliferation and migration, arrests the cell cycle at the G2/M phase in vitro, and inhibits tumor growth in vivo." (PMID 27888627, 2016). "In summary, ISG15 was up-regulated in NPC and predicted frequent tumor recurrence and poor outcome in patients." (PMID 26919245, 2016). "Therefore, whether ISG15 is a tumor suppressor or tumor promoter in vivo remains controversial." (PMID 25749047, 2015). "However, whether ISG15 promotes or suppresses tumor growth in vivo remains controversial." (PMID 25749047, 2015). "An interferon gene signature was also present in the profiles derived from the tumor epithelium of the ER-positive tumors (e.g., STAT1, IFIT1, IFIH1, IFI27, ISG15, OAS1, OAS3, OASL) and ER-negative tumors (e.g., HLA-DQA1 and HLA-DQB1)." (PMID 19225562, 2009). "Adoptive transfer of ex vivo-generated ISG15+MHC-I+ neutrophils in mouse models enhanced intratumoral CD8+ T cell infiltration, synergizing with anti-PD-1 therapy to suppress tumor growth." (PMID 41824789, 2026).